H19 (H19 imprinted maternally expressed transcript)
Diseases named in the same sentence as H19 in open-access papers (continued):
Sharing a sentence is not in itself a finding about the gene and the disease.
tumor (continued). "These non-clinical proof-of-concept studies support a potential clinical efficacy for BC-819 in patients whose tumor cells express H19 RNA." (PMID 26623562, 2016). "Similar to human lincRNA-p21, which is induced by hypoxia, other lncRNAs, including H19 and lncRNA-low expression in tumor (LET), are regulated by hypoxia and are involved in hypoxia-induced signaling transduction in cancer." (PMID 26735578, 2016). "Noticeably, high expression of H19 in CRC had a significant correlation with the tumor differentiation (P = 0.006) and advanced TNM stage (P = 0.026)." (PMID 26989025, 2016). "H19 has been observed to be transcriptionally upregulated in a number of tumours, and this upregulation is correlated with the increased metastatic potential of several tumours." (PMID 27152123, 2016). "We observed higher expression of H19 was significantly correlated with tumor differentiation and advanced TNM stage in a cohort of 83 CRC patients." (PMID 26989025, 2016). "As the mature product of H19, H19-derived miR-675 regulated tumor cell proliferation through downregulation of its targets, tumor suppressor retinoblastoma (RB), and Runt-related transcription factor 1 (RUNX1)." (PMID 26198047, 2016). "Downregulation of H19 expression in K562 cells affected cell survival and attenuated tumor formation in xenograft mouse model suggesting a functional involvement of H19 in Bcr-Abl-mediated cellular transformation." (PMID 27177333, 2016). "H19, also known as imprinted maternally expressed transcript, is only expressed from maternally-inherited chromosome and serves as a tumor suppressor in several types of cancer." (PMID 27429196, 2016). "Meanwhile, the expression of H19 was associated with histological grade, TNM, and tumor invasion depth in GC." (PMID 27672656, 2016). "In this particular study it was also shown that the anti-diabetic drug metformin, which is known to have anti-cancer activity, can inhibit tumor cell migration and invasion partly by down-regulating H19 epigenetically by DNA methylation of its promoter." (PMID 26623562, 2016). "Dysregulation of lncRNA H19 has been observed in various tumors, and it was described acting either as an oncogene or a tumor suppressor." (PMID 27177333, 2016). "Further analysis in a multivariate Cox proportional hazards model showed that H19 expression, together with TNM stage and tumor differentiation, were strongly associated with DFS (P = 0.018, P = 0.007, P = 0.009, respectively)." (PMID 26989025, 2016). "For example, H19, an imprinted gene, has both tumour suppression and oncogenic properties in cancer." (PMID 27733185, 2016). "More recently we found that the keratinocytes from these mice over express long non-coding RNA (lncRNA) oncogenes such as H19 and under express lncRNA tumor suppressors such as lincRNA-21." (PMID 27462278, 2016). "It is likely that H19 plays different roles in different tissues or developmental stages, and its role in a specific tissue remains the same in both normal and tumor cells." (PMID 26983719, 2016). "Remarkably, a tumor suppressor function of H19 has been demonstrated in vivo by using three different mice models of tumorigenesis." (PMID 25861629, 2015). "Another relatively very long (~120 KB) and short lived transcript called 91H spans the H19 gene locus and possesses tumor promoting activity, and is transcribed also in an antisense direction." (PMID 25884481, 2015). "Four weeks after injection, compared with control groups, H19-overexpressing cells displayed significant increase in the tumor size." (PMID 26068968, 2015). "H19 upregulates transcription of angiogenic genes and thus enables blood supply to the proliferating tumor." (PMID 26536864, 2015). "Expression of a DNA-based therapeutic toxin transcriptionally driven by IGF2-P4 or H19 promoters is predicted to occur in a manner specific for tumor expressing these gene products." (PMID 25884481, 2015).
tumor (continued). "Cells expressing H19 are able to form bigger colonies in soft agar and subcutaneous injection of H19 into mice promoted tumor progression." (PMID 26376677, 2015). "In this review we delineate the various functions of H19 during the different stages in the complex process of tumor progression." (PMID 26536864, 2015). "In Mitalipov's study, he suggested that hypermethylation within the IGF2/H19 IC in all analyzed primate ESC lines resulted in a risk of cellular overproliferation and tumor formation." (PMID 25879223, 2015). "H19 role in tumorigenesis is controversial, since it has been described as either protumorigenic or tumor suppressor depending on the context." (PMID 25861629, 2015). "By association with enhancer of zeste homolog 2 (EZH2), a well-established mediator of tumor metastasis, H19 upregulates Wnt/β-catenin signaling, which in turn represses E-cadherin expression." (PMID 26536864, 2015). "SCID-Beige mice transplanted with H19 down-regulated hEC cells exhibited slower kinetics of tumor formation, resulting in an increased animal survival." (PMID 26415227, 2015). "Other notatble lncRNAs such as HOTAIR, H19 and SRA become up-regulated with increasing EC tumour grade and other features associated with poor prognosis." (PMID 26556343, 2015). "It has been proposed that H19 acts as a tumor suppressor in Wilm's tumors, embryonic rhabdomyosarcoma, and the Beckwith-Wiedemann syndrome." (PMID 26353930, 2015). "In fact level of H19 expression shows significant correlation with tumor grade and is a potential biomarker for various cancers." (PMID 26082843, 2015). "Our results provided further evidence that plasma H19 levels can be used to distinguish early stage GC patients from controls to a clinically satisfactory degree compared with conventional tumor markers." (PMID 26096073, 2015). "Its role in tumor initiation and progression has long been a subject of controversy, although accumulating data suggest that H19 is one of the major genes in cancer." (PMID 26536864, 2015). "We previously demonstrated that in skeletal muscle and tumor cells H19 functions to reduce the bioavailability of let-7 by acting as a molecular sponge." (PMID 26089099, 2015). "Our results provided evidence that plasma H19 levels can be used to distinguish early stage GC patients from controls to a clinically satisfactory degree compared with conventional tumor markers." (PMID 26096073, 2015). "The BC-819 plasmid takes advantage of the tumor specific expression of H19 and acts as a “trojan horse” to kill cancer cells through the expression of DTA." (PMID 26064090, 2015). "Upon direct binding of c-Myc to H19, H19 gene transcription was significantly induced through histone acetylation in tumor cells." (PMID 26230711, 2015). "One is the comparison between expression of H19 in plasma and primary tumor tissue, which demonstrated that plasma and primary GC tissue samples showed that high levels of plasma H19 represented higher expressions in primary GC tissues than in normal mucosa." (PMID 26096073, 2015). "Delayed tumor formation and a decrease in tumor size were observed in tumors derived from down-regulated H19 cells compared to shLuc transduced cells." (PMID 26415227, 2015). "It is interesting to note that most of the down regulated probes pointed to H19 (imprinted maternally expressed transcript), which was previously reported to be a tumor suppressor and its methylation status correlated with smoking." (PMID 26159226, 2015). "Invasiveness and metastatic potential of tumor cells are associated with the process of EMT and H19 has been demonstrated to influence different players involved in this trans-differentiation phenomenon." (PMID 25861629, 2015). "On the contrary, healthy uterine stroma-cells present with higher levels of H19 as compared with stromal tumours." (PMID 26556343, 2015).
tumor (continued). "Conversely, H19 has been found to regulate the rate of tumor metastasis in advanced stages of HCC via the epigenetic activation of the miR-200 family." (PMID 25861629, 2015). "Another comprehensive study in murine KO models isolated the H19 deletion effect from the effect of Igf2 overexpression, which commonly accompanies H19 deletion, and showed in several tumor models that H19 has tumor suppressing properties." (PMID 26536864, 2015). "The H19 locus is host to a multitude of maternally imprinted coding and non-coding transcripts including H19, miR-675, H19 opposite tumor suppressor (HOTS), and 91H." (PMID 25101115, 2014). "Hypoxia elevated H19 abundance in HHC cells and H19 knockdown significantly reduced tumor growth after recovery following hypoxia." (PMID 25543668, 2014). "H19 expression in hepatic metastases arising from 9 different primary tumor types has also been evaluated." (PMID 25101115, 2014). "We confirmed this result and explored the effect of gender and PHx on H19 expression using qRT-PCR of tumor and non-tumor RNA samples from untreated (13-14-month-old) and post-PHx (9-month-old) livers from Mdr2-KO males and females." (PMID 25401338, 2014). "The microarray data demonstrated a very high expression of the H19 transcript in the non-tumor liver of hepatectomized females." (PMID 25401338, 2014). "The level of H19 expression was also strongly correlated with tumor invasion of the reproductive organs and significantly correlated with neoplastic cell invasion of the myometrium." (PMID 23429271, 2013). "H19 RNA alters expression profiles of genes involved in metastasis and blood vessel development, supporting the notion of a role for this gene in tumor invasion and angiogenesis." (PMID 23429271, 2013). "The H19-DTA vector exploits a tumor-selective promoter in conjunction with a cytotoxic gene to achieve targeted tumor cell destruction." (PMID 23984081, 2013). "H19 is essential for human tumor growth and metastasis through its interaction with several proteins." (PMID 24006935, 2013). "Our results indicate the importance of H19 gene expression for the tumor under stress conditions, induced by poor vascularization and characterized by poor oxygen and growth factors availability." (PMID 23429271, 2013). "In accordance with this, several lines of evidence support the involvement of H19 RNA in tumor progression through the metastatic pathway triggered by hypoxic stress." (PMID 23429271, 2013). "Downregulation of H19 by RNAi blocks cell growth and clonogenicity of lung cancer cell lines and decreases xenograft tumour growth of a hepatocellular carcinoma cell line." (PMID 23887658, 2013). "In this section, we'll focus on four transcriptional modulators of the H19 gene and discuss them in the context of the tumor-promoting activity of H19 RNA." (PMID 23429271, 2013). "Antisense to the H19 gene, the human H19 locus, encodes a translated product, called HOTS, for H19 opposite tumor suppressor." (PMID 23429271, 2013). "This treatment is therefore being paired with tumor tissue screening for the presence of H19 ribonucleic acid (RNA)." (PMID 23429271, 2013). "Of note, the H19 RNA was reported to encode at least one microRNA, proposed to negatively affect cell proliferation, which would be consistent with the role of H19 as a tumor suppressor." (PMID 23069990, 2013). "Regarding its role in tumorigenicity, it should be mentioned that although the prevailing view is that H19 is behaving like an oncogene, yet, several groups reported H19 as possessing a tumor suppressor activity." (PMID 23429271, 2013). "In recent years, it has become increasingly clear that H19 gene expression is essential for human tumor growth and is regulated by a complex interplay of malfunctioning factors that are reported to play a critical role in tumorigenesis." (PMID 23429271, 2013). "Downregulation of H19 gene expression was identified as an early event in the formation of several tumor types." (PMID 23711233, 2013).
tumor (continued). "The results of the present study indicate that H19 exerts both tumor-promoting and tumor-suppressing effects in choriocarcinoma cells, at least in part, by regulating cell proliferation and apoptosis." (PMID 23711233, 2013). "Similar observations have been made in trophoblast tissue; some studies revealed that H19 has tumor-suppressing activity, while others suggested that it has tumor-promoting activity." (PMID 23711233, 2013). "In recent years, we have extensively investigated the expression of the H19 gene in a number of human cancers and explored the role of H19 RNA in tumor development." (PMID 23429271, 2013). "And prominent expression of H19 was found in placental site trophoblastic tumor and gestational choriocarcinoma." (PMID 23711233, 2013). "They further found that H19 was associated with angiopoietin (ANG) and fibroblast growth factor-18 (FGF-18), whose functions are involved in tumor growth and proliferation." (PMID 24063685, 2013). "Given the strong association of H19 and Myc expression, the essential role of H19 in transformation suggests that Myc-induced H19 expression contributes to tumor etiology and the strong oncogenic behavior of Myc." (PMID 23429271, 2013). "A significant difference in tumor growth progression was found between the group of BC-819 + gemcitabine versus Luc-H19 + gemcitabine (P < 0.037)." (PMID 22701803, 2012). "Cancer cells devoid of H19 expression encounter a very significant retardation of tumor growth in vivo." (PMID 22701803, 2012). "One can note that an H19 antisense transcript called H19 opposite tumor suppressor (HOTS) was recently found in human." (PMID 22662250, 2012). "As such, a plasmid-based system has been developed to exploit the tumor-specific expression of H19, primarily tested in treating bladder cancer." (PMID 21489289, 2011). "Expression of diphteria toxin A fragment inevitably destroys cells by immediate disruption of protein synthesis and the H19 promoter restricts its expression to tumor cells." (PMID 21687669, 2011). "As H19 promoter is active only in malignant cells and during embryogenesis, tumor tissue is destroyed, while healthy tissue stays unharmed." (PMID 21687669, 2011). "Because the presence of the non-coding RNA H19 is crucial for the efficacy of BC-819, we examined tumor tissue for the presence of non-coding H19 RNA." (PMID 21687669, 2011). "H19-DTA-P4-DTA exhibited superior ability to inhibit heterotopic tumor development by 70% (P < 0.001) compared to H19-DTA or P4-DTA activity." (PMID 21162716, 2010). "We demonstrated that although the treatment consisted of an injection of naked DNA into the tumor, the vector indeed entered the cells and the H19 sequence was effective in leading to the DT-A gene expression." (PMID 21052499, 2010). "As expected, DTA-H19 treatment was effective in inhibiting the tumor growth compared with the Luc-H19 treated tumors." (PMID 21052499, 2010). "Mice treated with H19-DTA-P4-DTA exhibited a 61% (P < 0.001) reduction of the ex-vivo tumor volume and a 54% (P = 0.002) reduction of the ex-vivo tumor weight compared to H19-Luc-P4-Luc treated mice." (PMID 21162716, 2010). "Tumors were generated into athymic nude mice back by subcutaneous injection of CRL-1469 cells and then treated with DTA-H19 (n = 7) or Luc-H19 (n = 8, control group) plasmid by direct injection into the tumor." (PMID 21052499, 2010). "Three injections of H19-DTA or P4-DTA at two-day intervals were able to inhibit tumor development by 49% (P = 0.001) and 55.5% (P = 0.005), respectively compared to H19-Luc and P4-Luc treatments." (PMID 21162716, 2010). "Intratumoral injection of the toxin vector under the control of the H19 regulatory sequences induced a 50% decrease in the median tumor volume as compared to that of the tumor treated with the Luc-H19 vector." (PMID 21052499, 2010).
tumor (continued). "The double promoter construct thus exhibited enhanced ability to inhibit tumor development in vivo, compared to each of the single-promoter constructs (H19-DTA, or P4-DTA)." (PMID 21162716, 2010). "H19 knockout mice are viable and display an overgrowth phenotype and H19 has recently been shown to be a tumor modifier." (PMID 19956719, 2009). "At least 40% inhibition of tumor growth by DTA-H19/PEI was obtained compared to tumors treated with the control plasmid Luc-H19/PEI (P < 0.05)." (PMID 19656414, 2009). "H19 mRNA levels were higher in 13 HB tumours with ROI than in 7 HB tumours with IGF2 alterations (P<0.01 by Welch's t-test)." (PMID 19034281, 2008). "In contrast, 7 tumours with IGF2 alterations expressed very low levels of H19 mRNA, whereas 11 of 13 tumours with ROI expressed a substantial amount of H19 mRNA; 2 tumours (nos." (PMID 19034281, 2008). "De-differentiation, as occurs in tumor cells, generally results in a re-expression of H19 in various cell types." (PMID 18183302, 2008). "Further studies are necessary to unfold the molecular mechanism(s) controlling the expression of the imprinted gene H19 and its role in tumor development." (PMID 17786216, 2007). "The objective of this study is to explore the role of H19 in carcinogenesis, and to determine its identification as an anti-tumor target." (PMID 17786216, 2007). "Our results highlight a critical role of H19 RNA in tumor development, and in particular in the growth of HCC." (PMID 17786216, 2007). "More striking is the predictive value of H19 RNA for tumor recurrence, and its prognostic significance." (PMID 17786216, 2007). "Altogether, these data coupled with a wealth of information in the literature on the high expression level of the H19 gene in tumor tissue, identify H19 as having a pivotal role in tumor development." (PMID 17786216, 2007). "In this study, we used a powerful gene-silencing strategy (RNAi) to knock down the H19 RNA in cellular and animal tumor models." (PMID 17786216, 2007). "It is intriguing that three tumours (#23–25) showed alterations of both IGF2/H19 and KIP2/LIT1 imprinted domains, because each domain is independently regulated, and BWS with both alterations is very rare." (PMID 16909133, 2006). "The total number of tumours showing H19-pro-DMR hypermethylation was 21, comprising 11 with ROH and 10 with LOH." (PMID 16909133, 2006). "A total of 25 (71%) tumours showed alteration of IGF2/H19 or KIP2/LIT1 or both of the domains, of which 10 showed LOH, 11 showed IGF2 LOI only, one showed DMR-LIT1 hypomethylation only, and three showed both IGF2 LOI and DMR-LIT1 hypomethylation." (PMID 16909133, 2006). "In multivariate analysis, only advanced patient age (p < 0.001) and large tumor size (p = 0.002) remained independently associated with worse OS, irrespective of H19 expression (HR: 0.655; 95% CI: 0.367–1.170; p = 0.153) or histology (p > 0.05)." (PMID 41521159, 2026). "Tumor-associated fibroblasts exhibited significant heterogeneity, with cancer-associated fibroblasts (CAFs) expressing EMT-related genes and interacting closely with H19 + myoEpC." (PMID 41761191, 2026). "Our study is limited by inter‐patient variability, histological diversity, and sample size, which may have masked subtle differences in H19 expression between tumor sites." (PMID 41521159, 2026). "The functional inhibition of H19 restores chemosensitivity and radiosensitivity in resistant tumor cells, while exosome-mediated transfer of H19 contributes to the horizontal propagation of resistant traits within the tumor microenvironment." (PMID 41149459, 2025). "Reduced expression of the H19 gene, a maternally expressed long non-coding RNA with tumor-suppressive properties, may have important implications in Beckwith–Wiedemann syndrome." (PMID 41262921, 2025). "Additionally, H19 regulates the methylation of Beclin1, which activates autophagy and enhances tumor resistance to both chemotherapy and EGFR-TKI." (PMID 40723840, 2025).